ATR (ATR checkpoint kinase)
Diseases named in the same sentence as ATR in open-access papers (continued):
Sharing a sentence is not in itself a finding about the gene and the disease.
cancer (continued). "The first reported ATR-selective small-molecule inhibitor, Schisandrin B (SchB), abrogated ATR kinase activity and therefore, ATR-mediated UV-induced intra-S-phase and G2/M cell cycle checkpoints, sensitising cancer cells to UV radiation." (PMID 29757235, 2018). "On the other hand, ectopic expression of ATR suppressed the expression/secretion of several cancer-promoting proteins such as IL-6, TGF-β1 and SDF-1, and inhibited the migration and invasion capacities of breast myofibroblast cells." (PMID 30410668, 2018). "Given the central role of ATR in responding to replication stress and the prevalence of replication stress in cancer, ATR inhibitors are now under investigation as anti-cancer therapeutics." (PMID 30544989, 2018). "This indicates that ATR negatively controls the expression/secretion of these cancer-promoting proteins in breast stromal fibroblasts." (PMID 30410668, 2018). "Many studies have reported that genetic variants in ATR/CHEK1 and ATM/CHEK2 are associated with cancer risk." (PMID 29928473, 2018). "Our next goal was to dissect the role of ATR in the signaling network operating during cancer cell senescence." (PMID 29352261, 2018). "In vitro, it has been shown that inhibition of ATM or ATR can sensitize cancer cells to genotoxic agents, highlighting their potential as therapeutic targets." (PMID 29757235, 2018). "Our results support the idea that ATR inhibition is an efficient anti-cancer strategy and demonstrate an important novel aspect of ATR function in G1." (PMID 29720710, 2018). "A recent study has found that cancer cells with an ALT profile are hypersensitive to ATR inhibitors." (PMID 29848986, 2018). "Activation of the ATR–Chk1-dependent response is observed in early cancer precursors indicating the presence of RS." (PMID 29950452, 2018). "The checkpoint kinase ATR plays important roles both in response to DNA damage and replication stress, and ATR inhibitors are currently in clinical trials for cancer treatment." (PMID 29720710, 2018). "This surprising finding is highly relevant for the use of ATR inhibitors in cancer therapy and the cytostatic effects should be taken into account when future clinical trials employing ATR inhibitors are performed." (PMID 29720710, 2018). "ATR is therefore seen as a promising target for cancer therapy and clinical trials exploiting specific ATR inhibitors (ATRi-s) for their cytotoxic effect are ongoing." (PMID 29720710, 2018). "Taken together, selective targeting of the ATR/Chk1 pathway offers a promising therapeutic approach for cancer treatment in a broad range of tumours in both monotherapy and for the purpose of selectively sensitizing cancer cells to current genotoxic treatment." (PMID 30001349, 2018). "It was recently shown that APOBEC3A/B expressing cancer cells are sensitive to ATR inhibitors owing to the resulting replication catastrophe." (PMID 30417129, 2018). "Nevertheless, such cancer cells often retain a G2 checkpoint, in particular a chromatin-quality checkpoint in late G2 involving ATR/p38/MK2." (PMID 29882812, 2018). "This differential expression suggests that ATR down-regulation in CAFs is due to the presence of these cells close to cancer cells, which perturbs the microenvironment through paracrine signaling." (PMID 30410668, 2018). "We discovered that PD-L1 upregulation in cancer cells is ATM/ATR/Chk1-dependent after IR or treatment with CPT, APH or Etp." (PMID 29170499, 2017). "Alternatively, cancer cells treated with Olaparib would create a need for ATR activity that likely promotes cell cycle check-point activation and DNA repair." (PMID 29348879, 2017).
cancer (continued). "Studies using early inhibitors such as UCN-01 and NU6027 provided much proof of principle and mechanistic evidence for the use of small molecule inhibitors of CHK1 and ATR, respectively in an anti-cancer setting." (PMID 28448462, 2017). "WEE1 inhibition sensitizes TNBCs and cisplatin resistant cancer cells to cisplatin-induced lethality, because it not only impairs DNA replication checkpoint more profoundly than inhibition of ATR or CHK1, but also defects G2-M cell cycle checkpoint." (PMID 28262781, 2017). "As a result of this the S/G2 checkpoint and thus the ATR/CHK1 pathway is an attractive target for cancer-specific therapy." (PMID 28448462, 2017). "DNA damage caused by radiation, UV light, or anti-cancer agents results in phosphorylation of Histone γ-H2A.X at ser-139 by PI3K-like kinases, including ATM, ATR, and DNA-PK." (PMID 28157696, 2017). "Defects in both the BER and NER pathways have been reported in a variety of different cancer types highlighting the clinical potential for ATR and CHK1 inhibitors." (PMID 28448462, 2017). "When compared with 31 cancer cell lines of different origins, p185BCR-ABLArf–/– cells were amongst the most sensitive to ATR inhibition by VE-822, with an IC50 value of ~ 300 nM." (PMID 28808226, 2017). "VX-970 (VE-822), a potent selective intravenous ATR kinase inhibitor, was the first ATR inhibitor to go into human anti-cancer drug trials." (PMID 28448462, 2017). "Taken together, our findings provided an advanced NTP regimen for cancer treatment by combining NTPO treatment with chemical adjuvants for the inhibition of ATR- and PARP1-activated DNA damage responses, and circadian timing of treatment." (PMID 27145275, 2016). "Inhibition of ATR/Chk1 pathway has been shown to sensitize cancer cells to gemcitabine, cytarabine and 5-fluorouracil." (PMID 27246979, 2016). "For example, whereas VP-16 provokes ATR activation, camptothecin activates either ATM or ATR in DNA damage events in different cancer cell lines." (PMID 26683224, 2016). "Oncogene-induced replication stress (RS) is a known source of endogenous DNA damage in cancer, which is suppressed by ATR and CHK1 kinases." (PMID 27577084, 2016). "In summary, we believe ATR can be used to develop a novel innovative immunotherapeutic approach for cancers." (PMID 27602488, 2016). "These cancer cells are more sensitive to the partial inhibition of ATR/Chk1/Wee1 kinases compared to the healthy counterparts." (PMID 26295265, 2015). "The third strategy exploits genetically-determined defects in DNA repair pathways (mostly homologous recombination) that render cancer cells more sensitive to PARP or ATR/Chk1/Wee1 inhibitors." (PMID 26295265, 2015). "In fact, Weber and Ryan suggested that ATM and ATR can serve as therapeutic targets either as a monotherapy in cancers with DDR defects, or as a combinatorial therapy in other relevant cancers." (PMID 26404381, 2015). "While its role as an ATR inhibitor is promising, further studies are needed to validate SchB as a sensitizing agent for anti-cancer therapy." (PMID 26610585, 2015).
cancer (continued). "The second strategy relies on addiction of cancer cells transformed by active oncogenes (such as Ras, Myc or Cyclin E) to ATR, Chk1, and Wee1 kinases that allow them to cope with a high level of replication stress." (PMID 26295265, 2015). "ATR inhibition synergizes with DNA damaging chemotherapy drugs such as cisplatin and gemcitabine to kill cancer cells." (PMID 25965342, 2015). "ATR is an essential kinase, and many cancer cells have an increased dependence on ATR to compensate for oncogene-induced replication stress." (PMID 25965342, 2015). "As such, the ATR-Chk1 pathway is a potential target for anti-cancer therapy and ATR-selective inhibitors are currently in development." (PMID 26257651, 2015). "Our results strongly suggest that G2E3 depletion alleviates ATR-Chk1 signaling and enhances replicative stress in cancer cells." (PMID 25593194, 2015). "Taken together, these results suggest that G2E3 depletion decreases ATR-Chk1 signaling and increases replicative stress in gemcitabine-treated cancer cells." (PMID 25593194, 2015). "ATR inhibitors are in clinical trials for the treatment of many forms of cancer and show strong synergy with cisplatin and other DNA damaging chemotherapy agents." (PMID 25965342, 2015). "The cytotoxic effect can be explained by the addiction of hyper-replicating cancer cells to the ATR/Chk1/Wee1 signaling that protects them from replicative catastrophe." (PMID 26295265, 2015). "While the in vitro data is convincing, an in vivo xenograph model would be more compelling evidence to suggest that combining BO-1055 and ATM/ATR inhibitors effectively decreases the survival of cancer cells." (PMID 26208482, 2015). "Accordingly, ATR inhibition by VE-821 leads to the inhibition of radiation-induced G2/M arrest in cancer cells." (PMID 26610585, 2015). "Further, loss of DDR components ATM, ATR, or CHK1 lead to either embryonic lethality in mice and/or a predisposition for cancer." (PMID 25898113, 2015). "To provide evidence that such an approach is feasible, we have recently shown that XRCC1-deficient cancer cells are sensitive to ATM, DNA-PKcs, and ATR inhibitors." (PMID 25111287, 2014). "Cancer cells have an increased dependence on the ATR pathway due to high levels of oncogene-induced replication stress and frequent loss of the G1 checkpoint." (PMID 24901225, 2014). "Inhibition of ATR or its downstream substrate, Chk1, has been shown to sensitize cancer cells to certain DNA damaging drugs and ionizing radiation (IR)." (PMID 25010037, 2014). "This, coupled with biomarker data showing blockade of ATR activity and accumulation of DNA damage is consistent with the anti-cancer activity of VX-970 being driven by inhibition of ATR and subsequent impaired DNA damage repair." (PMID 25010037, 2014). "We show here a powerful phosphoproteomic approach for investigation of the role of ATR-mediated signaling in the context of radiosensitization of cancer cells." (PMID 25003641, 2014). "Similar to cancer cells in which HDAC3 was depleted by shRNA, Hdac3-deficient MEFs also exhibited decreased expression levels of BRCA1 and ATR but increased levels of CHK1 and γ-H2AX." (PMID 25026298, 2014). "Our results support a proposal that inhibition of ATR will provide a new approach to improve patient responses to the DNA damaging agents that form the current standard-of-care across many cancer indications." (PMID 25010037, 2014). "For example, VP-16 elicits primarily ATR activation, however, camptothecin activates either ATM or ATR in DNA damage events in different cancer cell lines, to some extent, was similar to RD in PCa cells." (PMID 24069304, 2013). "Although the therapeutic potential of caffeine for causing premature chromosome condensation in G1 checkpoint-compromised cancer cells has long been recognized, the concentrations needed to fully inhibit ATR kinases are toxic." (PMID 23555814, 2013).
cancer (continued). "Further studies are needed to elucidate the relationships among MAGE proteins, Smc5/6 components, and proteins such as ATM and ATR that are also important for resistance to genotoxic agents in normal and cancer cells." (PMID 23555814, 2013). "Small molecule inhibitors of ATR are currently under development for therapeutic application in cancer." (PMID 23451157, 2013). "The central roles of ATM and ATR in genome maintenance suggest the potential to manipulate their activity for cancer chemotherapy, fueling the development of potent small molecules that specifically inhibit ATM and ATR activities in cellulo." (PMID 23592994, 2013). "Gene and protein expression profiles of Ag-np exposed cells revealed up regulation of many DNA damage response genes such as Gadd 45 in both the cell types and ATR in cancer cells." (PMID 22321936, 2012). "Genetic analyses indicated that early in tumourigenesis (before genomic instability and malignant conversion), human cells activate an ATR/ATM-regulated DNA damage response network that delays or prevents cancer." (PMID 21747934, 2011). "Recently, we reported that COX-2 overexpressing cancer cells upregulate ataxia telangiectasia and rad3-related (ATR) expression and activity, and that upregulated ATR induces resistance to DNA damaging agents such as IR or hydroxyurea." (PMID 20731837, 2010). "We will discuss the importance of fragile sites, direct evidence of their involvement in cancer, sequence characteristics of fragile sites that contribute to their instability, and the role of the ATR-dependent DNA damage checkpoint pathway in their breakage." (PMID 21286310, 2010). "More research is necessary to better understand the mechanism of the ATR pathway at fragile sites and its effect on cancer development." (PMID 21286310, 2010). "Inhibiting ATM, ATR or their downstream targets thus serves to widen the therapeutic window of genotoxic anti-cancer therapeutics by sensitizing cancer cells to these agents (reviewed)." (PMID 19903334, 2009). "These and other data indicate that early in tumorigenesis, before malignant conversion, human cells activate the ATM- and ATR-dependent DNA damage response, which delays or prevents cancer." (PMID 18577246, 2008). "Specifically, we observed ATM/ATR-dependent increase in expression of PD-L1 on the cancer cells." (PMID 42094069, 2026). "Recent studies show that inhibition of key RS response kinases such as ATR, Chk1, or Wee1—which cancer cells depend on to survive under RS—can tip the balance toward mitotic catastrophe, especially when combined with genotoxic therapy or in tumors with high intrinsic RS." (PMID 41614897, 2026). "This review focuses on the molecular origins of RS in cancer, its impact on DNA damage responses and radiosensitivity, and current therapeutic efforts to exploit replication-stress vulnerabilities—particularly through inhibition of ATR, Chk1, Wee1, and PARP." (PMID 41614897, 2026). "Replication stress and the increased sensitivity to ATR/CHK1 inhibition could represent a vulnerability of YAP-dependent cancers that can be exploited therapeutically." (PMID 40615577, 2025). "The NCI/Cancer Therapy Evaluation Program Project Team carefully evaluated the results of completed and ongoing ATR inhibitor studies, as well as the known pharmacokinetic (PK) data for elimusertib, to establish evidence-based dose schedules for combination regimens." (PMID 41104717, 2025). "Resistance arises when cancer cells develop efficient DNA damage repair mechanisms by activating regulators of DNA damage response, including ataxia-telangiectasia mutated (ATM) and ataxia-telangiectasia and Rad3-related (ATR) proteins." (PMID 41335461, 2025). "The potential of ATR inhibition in cancer therapy has also attracted much attention." (PMID 40573290, 2025).
cancer (continued). "Thus, ATR inhibitors can selectively kill cancer cells while preserving normal cells with intact DDR." (PMID 40240755, 2025). "Although ATR inhibitors hold great promise for the treatment of cancer, challenges remain, including the identification of reliable biomarkers to predict response to ATR inhibitors and concerns about toxic off-target effects in normal cells that undergo replication stress to a lesser extent." (PMID 41392982, 2025). "In cancer, ATR inhibitors are currently under clinical development, and our results demonstrate that these inhibitors will have pleotropic effects outside of the DNA damage response that may influence therapeutic efficacy." (PMID 40514450, 2025). "Targeting the DNA damage response signaling kinase, ATR (ataxia telangiectasia and rad3-related serine/threonine kinase), activated in response to PARPi-induced replication stress, represents a promising approach in fighting PARPi-resistant cancers." (PMID 39968096, 2025). "Moreover, the loss of DNA repair proteins, such as XRCC1 and ERCC1, enhances the vulnerability of cancer cells to ATR inhibitors, as demonstrated in preclinical models." (PMID 40256842, 2025). "Moreover, the loss of PARP5B activated the ataxia telangiectasia and Rad3‐related (ATR) protein and diminished cancer stem cells." (PMID 40904702, 2025). "Noteworthy to mention that the drug discovery endeavours employed robust drug design strategies and culminated into a plethora of tractable ATM/ATR/DNA-PK inhibitors that on exhaustive explorations might emerge as cancer therapeutics in the long run." (PMID 40256842, 2025). "We also believe there is a need for future work to determine whether the effects of ATR inhibitors to suppress mTORC1 in normal cells, especially immune cells, is counteractive to its effects on the cancer cells themselves." (PMID 40514450, 2025). "siRNA-mediated POLA1 depletion sensitized several cancer cell lines to ATR and Chk1 inhibitors." (PMID 40422251, 2025). "Several ATM/ATR inhibitors have been reported to sensitize cancer cells to IR." (PMID 40332379, 2025). "There is resurging interest in targeting ATR and other DDR proteins in cancer due to DDR inhibitors causing an immunogenic cell death in vitro that could potentially enhance ICI therapy." (PMID 40491496, 2025). "However, when cancer cells undergo high levels of replication stress, they exploit ATR pathways to sustain their survival thus making ATR pathway activation an oncogenic event." (PMID 40940791, 2025). "Consequently, cancer cells rely heavily on the ATR pathway to cope with and tolerate replication stress, making ATR an attractive target for cancer therapy." (PMID 41392982, 2025). "Different class of ATR inhibitors used for cancer treatment." (PMID 40256842, 2025). "Extended from the study, ARID1A‐deficient cancer cells were found to be susceptible to Ataxia‐telangiectasia and rad3‐related protein kinase (ATR) inhibitors because these cancer cells show defects in topoisomerase 2A and cell cycle regulation, leading to a dependency in ATR function." (PMID 40621620, 2025). "Therefore, cancer cells that face genomic instability will more likely depend on the ATR pathway for survival." (PMID 40422251, 2025). "Importantly, a phase I clinical trial with an ATR inhibitor (PATRIOT) as a single agent in various cancer types showed promising results." (PMID 40139833, 2025). "Concomitant inhibition of ataxia telangiectasia and Rad3‐related protein (ATR) and poly ADP‐ribose Polymerase (PARP) pathways is a promising strategy in cancer therapy, potentially expanding the clinical utility of ATR inhibitor (ATRi) and PARP inhibitor (PARPi)." (PMID 40521858, 2025).